IL6 (interleukin 6)
Diseases named in the same sentence as IL6 in open-access papers (continued):
Sharing a sentence is not in itself a finding about the gene and the disease.
hematological malignancies (continued). "Other patients with no history of hematological malignancy also received early tocilizumab for septic shock, and IL-6 levels also dropped after tocilizumab administration." (PMID 40136690, 2025). "Other experimental potential biomarkers that are being tested in patients with hematologic malignancies are high-sensitivity CRP (Hs-CRP), interleukin-6 (IL-6), myeloperoxidase (MPO), fatty-acid-binding protein (FABP), glycogen-phosphorylase-binding protein (GPBP) and neuregulin-1 (NRG-1)." (PMID 39941907, 2025). "Among patients treated with tocilizumab, the IL-6 trend (D1 to D7) was significantly hematological malignancy compared to those without hematological malignancy." (PMID 40136690, 2025). "Trends in IL-6 levels (D1 to D7) were significantly higher in non-survivors compared to survivors and in patients with hematological malignancies compared to those without." (PMID 40136690, 2025). "Herein, we conducted a prospective study to investigate whether IL‐6, PCT, and CRP can be used to evaluate initial antibiotic efficacy of FN patients with hematological disorder through observing the early kinetic changes in these three biomarkers." (PMID 38967137, 2024). "Previous clinical trials have found that targeted IL-6 therapies provided no benefit in hematological malignancies, renal, and prostate cancer." (PMID 35260569, 2022). "Hematological disorders, such as hemoglobin concentration, negatively correlated with TNF-α, IL-6, IL-27 and IL-10 (all p ≤0.0005); Platelet and eosinophil counts were negatively correlated with TNF-α, IL-6, IL-27 and IL-10 (p ≤0.0005)." (PMID 26814478, 2016). "To explore the possible mechanism of SARS-CoV-2-induced blood disorders and inflammation by elevating IL-6 and IL-17, we carried out molecular docking to investigate PPIs between SARS-CoV-2 spike protein (S) and either unliganded IL-6R and IL-17R or complex forms IL-6/IL-6R and IL-17/IL-17R." (PMID 41184328, 2025).
dermatitis (59 papers, 2012 to 2026). An inflammatory process affecting the skin. "Excessive UV irradiation markedly increases the expression of inflammatory markers such as IL-6, IL-17, and TNF-α in skin epidermal and dermal cells, leading to inflammation and associated skin disorders." (PMID 39469625, 2024). "TNF-α and IL-6 are prominent cytokines in the pathogenesis of skin disorders." (PMID 33525403, 2021).
retinopathy (47 papers, 2007 to 2025). "However, we do not have direct evidence in our study and, therefore, cannot conclude that IL-6 is in any way causative of retinopathy progress." (PMID 28969616, 2017). "Altogether, our study represents a valuable investigation of gene expression changes induced by VEGF, TNF-α, and IL-6 and will aid researchers in selecting appropriate animal models for retinopathies based on their agreement with the human pathophysiology." (PMID 36371417, 2022). "Altogether, here we characterized the gene expression profiles of AAV-VEGF, TNF-α, or IL-6 driven retinopathy mouse models, and combined these measurements with publicly available singe-cell RNA expression data." (PMID 36371417, 2022). "Various pre-clinical rodent models have directly or indirectly shed light on the function of VEGF, TNF-α, or IL-6 in retinopathies." (PMID 36371417, 2022). "In summary, the long-term expression of human VEGF-A165, TNF-α, or IL-6 in the mouse eye induced specific pathologies within 6 weeks that mimic different aspects of human retinopathies." (PMID 34520511, 2021). "We hypothesize that this may be because serum IGF-1 and IL-6 are involved in the development of retinopathy." (PMID 36568065, 2022). "For example, elevated levels of tumor necrosis factor (TNF)-α, interleukin (IL)-8, and soluble IL-2 receptors were found in the serum of diabetic patients; increased vitreous concentrations of IL-6 and IL-8 were also found in patients with proliferative retinopathy." (PMID 22312190, 2012). "In addition, we have demonstrated that IL-6 strongly correlates with chemokines in the diabetic group (r=0.74 for CCL2; r=0.86 for CXCL8), indicating that the increased levels are likely downstream effects of elevated IL-6 seen in eyes with retinopathy." (PMID 22511846, 2012). "The inflammatory response in retinopathy is manifested as the overexpression of various inflammatory factors, such as tumor necrosis factor-α (TNF-α), interleukin-6 (IL-6), and cyclooxygenase-2 (COX-2)." (PMID 40717982, 2025). "The oxygen‐induced retinopathy model of AMD has increased senescent markers (p16Ink4a, p21Cip1 and SA‐β‐gal) and SASP, including Vegf, Il1β, Il6, Tgfβ1, and Pai1." (PMID 39604117, 2025). "They decreased the expression of IL-6 and TNF-α and the production of iNOS, while anti-inflammatory IL-10 was upregulated both in hypoxia-treated BV2 cells and a retinopathy mouse model through inhibition of the NF-κB pathway." (PMID 36768783, 2023). "Cytokines and growth factors including TNFα, IL-6, MCP1, and VEGF are upregulated in the vitreous of patients with proliferative retinopathy, and have been shown to mediate pathological neovascularization in OIR." (PMID 36038541, 2022). "Serum levels of IL-6 and TNF- α are proposed to be predictor of proliferative retinopathy development." (PMID 19784389, 2009). "Interestingly, P2X7−/− mice were protected from the NaIO3-induced retinopathy and inflammatory NLRP3, IL-1β and IL-6 gene expression in the retina." (PMID 36671003, 2023). "In the case of the dynamic inflammation level alterations in different retinopathy stages, clinical studies showed that serum IL-6 was significantly increased in both the nonproliferative DR and proliferative DR but not in no DR patients with T2DM." (PMID 34725563, 2021). "PDR patients also demonstrated significant upregulations of TNF-α and IL-6 in the VH when compared to the vitreous of non-diabetic patients without retinopathy." (PMID 29695738, 2018). "Compared to diabetic patients without retinopathy, only the IL-6 and VEGF levels were significantly higher in diabetic patients with retinopathy." (PMID 22511846, 2012). "In our study serum IL-6 level was more elevated in NDPR group than without retinopathy children and similar relations concerned the IL-6 positive sera in these groups." (PMID 17641733, 2007).
retinopathy (continued). "The NPDR children demonstrated a significantly longer duration of the disease in addition to higher HbA1c, albumin excretion rate, C-reactive protein, systolic blood pressure, as well as TNF-α and IL-6 levels than those without retinopathy." (PMID 17641733, 2007). "The serum levels of TNF-α and IL-6 in the group with NPDR were significantly higher as compared with children without retinopathy." (PMID 17641733, 2007). "Furthermore, the aqueous humor cytokine profile revealed that compared to diabetic patients without retinopathy, only the IL-6 and VEGF levels were significantly higher in diabetic patients with retinopathy." (PMID 23437353, 2013). "IL-6 was measurable in significantly more diabetic samples, and the median levels were significantly higher in the eyes with retinopathy than the eyes without retinopathy and the non-diabetic eyes." (PMID 22511846, 2012). "However, all the NPDR children (100%) had a detectable serum level of IL-6 and70% of children without retinopathy were IL-6 positive." (PMID 17641733, 2007). "Children without retinopathy were characterized by significantly higher TNF-α, IL-6, as well as IL-12 serum levels in relation to the healthy controls." (PMID 17641733, 2007). "Vitreous concentrations of IL-6 and IL-8 were significantly greater in patients with PDR than in noninflammatory retinopathies, and serum TNF-α was significantly greater in PDR than in noninflammatory retinopathies (this latter finding was limited to the serum but did not hold true in the vitreous)." (PMID 23028203, 2012).
vasculopathy (42 papers, 2007 to 2025). "IL-6 has an important role in both vasculopathy and fibrosis and is associated with various clinical manifestations." (PMID 35203527, 2022). "Given the suspected vasculopathy, the patient was initiated on tocilizumab, an IL‐6 inhibiting monoclonal antibody." (PMID 41245028, 2025). "IL6 plays a critical role in mediation of cell-mediated rejection, antibody-mediated rejection and graft vasculopathy in kidney transplantation." (PMID 32589662, 2020). "Increased levels of IL-6 also have been found in the cerebrospinal fluid of patients with vasculopathy in the brain, and IL-6 inhibits VZV replication in stem-cell derived neuronal cultures." (PMID 30568636, 2018). "Elevated IL-6 has been associated with heightened risks of allograft rejection and graft vasculopathy.Consequently, the exercise-induced reduction in IL-6 introduces compelling possibilities for alleviating these complications in individuals who have undergone heart transplantation." (PMID 38571360, 2024). "Also, we confirmed previous causal association for IL6 signaling in CAD and we extended these data to AAA, an atherothrombotic vascular disorder." (PMID 31552141, 2019). "In addition, it may prevent intimal proliferation and obliterative vasculopathy by IL-6 produced in endothelial cells." (PMID 33935762, 2021). "Finally, we tested the association of IL6 signaling in AAA, an atherothrombotic vascular disorder." (PMID 31552141, 2019). "Thus, systemic and local cytokine productions could be initiated and damage the CNS together with possible vasculopathy in the brain, as researchers have reported elevation of tumor necrosis factor-α, interleukin-6 (IL-6), and IL-10 in CSF in SLE patients." (PMID 29449817, 2018). "The cause of central nervous system inflammation and vasculopathy caused by NB may be the invasion of the central nervous system by Brucella, which interacts with astrocytes and microglia and induces the secretion of TNF-α, IL-1β and IL-6 by astrocytes and microglia." (PMID 38730327, 2024). "N153S animals have also been shown to overexpress IL-1β, IL-6, and MIP-1α in their lungs as an attribute of the vasculopathy they experience." (PMID 35769461, 2022). "Moreover, the production of IL-6 by binding of DSA to alloantigen on graft endothelium can stimulate intimal proliferation and obliterative vasculopathy, likely resulting in manifestations of chronic ABMR." (PMID 33935762, 2021). "However, the role of IL-6 in mediating SSc vasculopathy, and especially gastrointestinal (GI) vasculopathy, is not defined yet." (PMID 39802335, 2025). "The broad expression of IL-6, IL-17 and CD47/SIRP on erythrocytes, platelets, lymphohematopoietic cell, and endothelial and epithelial cells indicates their roles in cell differentiation, apoptosis, phagocytosis and cell-cell fusion, as well as many metabolic and vascular disorders." (PMID 41184328, 2025). "In SSc, vasculopathy and characteristic endothelial changes are prominent, along with inflammatory response skewed toward Th2 responses, IL-6, and TGF-β — features that we do not observe in PSM skin — suggesting that, despite shared profibrotic responses, these 3 diseases are largely distinct." (PMID 37471168, 2023).
liver (31 papers, 2015 to 2025). "Molecular evidence has demonstrated that inflammatory signaling pathways are upregulated in gastrointestinal neoplasms, especially NF-κB and IL-6." (PMID 33407508, 2021). "Novel data have identified TNF-α, IL-17A and IL-6 as crucial link between enhanced activity of immune system and colon carcinogenesis." (PMID 28881574, 2017). "Berberine can reduce the expression of pro-inflammatory cytokines IL-1, IL-6 and TNF- mRNA and CD68(markers of macrophages) in MICE with DSS-colonitis." (PMID 33019433, 2020). "Furthermore, an analysis of the effects of PCE on IL-6, IL-1β, and TNF-α expression in colonic epithelial cells of the rat colon carcinogenesis model showed an increase in IL-6, IL-1β, and TNF-α mRNA levels in the DMH + DSS group." (PMID 36900505, 2023).
peripheral neuropathy (30 papers, 2010 to 2025). A disorder affecting the peripheral nervous system. "Il-6, another well studied cytokine, also performs a crucial role in neuropathic pain caused by peripheral nerve injury, spinal cord damage, and chemotherapy-induced peripheral neuropathy." (PMID 37174675, 2023). "Paclitaxel increases IL-6, TNF-α, and CCL2 production in dorsal root ganglia neurons, and IL-6 neutralizing antibody pretreatment prevents peripheral neuropathy development, suggesting the role of increased inflammation in peripheral neuropathy development." (PMID 40759570, 2025). "The involvement of IL-6 was also demonstrated in peripheral neuropathy in animal models of sciatic cryoneurolysis and CCI of the sciatic nerve." (PMID 37174675, 2023). "Previous reports have shown that CD68-positive macrophages were activated on the sural nerves of patients with MPA with peripheral neuropathy, and IL-6 was overexpressed by CD68-positive macrophages in sural nerve specimens of vasculitic neuropathy." (PMID 36362162, 2022). "In a recent study in patients with peripheral neuropathy, IL-6 and IL-8 expression appeared to be sharply increased in skin biopsies, drawing attention to IL-8 and IL-6 as promising pharmacological targets for pain management." (PMID 31197114, 2019). "The expression of cytokines and chemokines is a prominent feature of neuroinflammation and elevated levels of certain cytokines, such as TNFα, IL-6, and IL-1β, have been demonstrated in patients with painful peripheral neuropathies, such as GBS and CIDP34–39." (PMID 28811623, 2017). "The involvement of IL-6 in peripheral neuropathy was first found in a rat model of sciatic cryoneurolysis (SCN), in which the sciatic nerve was frozen to induce nerve injury." (PMID 27267059, 2016). "The peripheral neuropathy is reported to be associated with MCP-1 induction, IL-1β release, and high levels of IL-6." (PMID 35273508, 2022). "In a separate RCT assessing diabetic neuropathy in patients with type 1 diabetes (T1DM), liraglutide was not shown to alter neuronal function; however, inflammatory cytokines like IL‐6 were reduced, which may modulate the neuroinflammatory component of peripheral neuropathy." (PMID 40888511, 2025). "These variables showed that nearly 50% of the variation in the data, including pro-inflammatory IL-6, IL-17A, TNF-α, and LPS, contributed significantly to peripheral neuropathy." (PMID 41264657, 2025). "Both the extracts of WS significantly reduced the signs of peripheral neuropathy accompanied by reduction in PTX-induced high levels of MCP-1, IL-1β, and IL-6." (PMID 35273508, 2022). "Taken together, it is worth noting that TNF-α and IL-6 in plasma and phospho-NF-κB and phospho-STAT3 in spinal cord and sciatic nerves are putative biomarkers of docetaxel-induced peripheral neuropathy (DIPN) in mouse models." (PMID 34422067, 2021). "It has been shown that inflammatory cytokines such as IL-1β, IL-6, and TNF-α are involved in the progression of BTZ-induced peripheral neuropathy." (PMID 32733956, 2020). "PRP or PRP gel has not been shown to suppress neuronal expression of TNF-α and IL-6 in peripheral neuropathy animal models." (PMID 40951078, 2025). "One study showed that high-dose vitamin D3 supplementation of 40,000 IU/week (~5700 IU/d) for 24 weeks was associated with improvement in clinical manifestation, cutaneous microcirculation and inflammatory markers (decreased IL-6 and increased IL-10) in patients with T2DM and peripheral neuropathy." (PMID 36558465, 2022). "Paclitaxel-induced peripheral neuropathy (PN) is a consequence of activation of the inflammatory cascade with subsequent increased pro-inflammatory cytokine production including tumor necrosis factor-α (TNF-α), interleukin-1β (IL-1β), and interleukin-6 (IL-6)." (PMID 35596774, 2022).
intestinal diseases (25 papers, 2013 to 2025). "During piglet production, weanling stress may induce intestinal disorders with increased pro-inflammatory cytokine secretion such as IL-1β, IL-6, and TNF-α, which cause growth retardation." (PMID 35814707, 2022). "One member of Fusobacterium, F. nucleatum has been recognized as an opportunistic pathogen that plays an important role in intestinal diseases, which promotes the inflammatory response and induces the release of the pro–inflammatory cytokines IL–6 and IL–8." (PMID 37958063, 2023). "Despite equine IL-6 being heavily researched for a multitude of diseases, there are limited studies with respect to the effect of intestinal diseases on serum and peritoneal fluid IL-6 concentrations." (PMID 36670767, 2023). "Because acute CWIR can occur in unusual environments and workgroups, such as floods, soldiers, and lifeguards, the findings offer a novel strategy for the treatment of CWIR-related intestinal disorders by inhibiting IL-6 signaling." (PMID 36505466, 2022). "The findings shed new light on treating CWIR-induced intestinal disorders by inhibiting IL-6 signaling." (PMID 36505466, 2022). "In intestinal disorders including IM, curcumin exerts its anti-inflammatory effects not only by inhibiting NF-κB activation but also contributes to its ability to regulate IL-6/STAT3 signaling." (PMID 34337082, 2021). "And studies focused on reducing symptoms of various intestinal diseases, such as IM, are always accompanied by lower IL-6 level." (PMID 34337082, 2021). "Proinflammatory cytokines such as IL-6, IL-8, and TNF-α are associated with the severity of inflammation and intestinal disease, which can directly affect intestinal epithelial cells." (PMID 33163144, 2020). "TNF-α and IL-6 in the serum are related to intestinal disease, and all are upregulated in IBD patients." (PMID 32714090, 2020). "It normally causes mucosal inflammation, intestinal ulcers, and histological damage and triggers colonic expression of the proinflammatory cytokines TNF-α, IL-1β, and IL-6 in 14 days after the TNBS administration." (PMID 25729217, 2015). "Many probiotics alleviate intestinal diseases by reducing IL-6 levels." (PMID 37960257, 2023). "In this manuscript, we found that IL-1β and IL-6 levels increased in CD enterocytes, not only in the acute phase of the disease but also in the remission phase and in potential patients before the onset of intestinal disease." (PMID 35216089, 2022). "This is in line with observations that dietary gangliosides can interrupt pro-inflammatory signalling via IL-1β in the intestinal mucosa, specifically suppressing production of IL-1β, NO, PGE2, hydrogen peroxide, IL-6 and IL-8, and subsequently alleviating symptoms of intestinal disease." (PMID 32679677, 2020). "Specifically, CEC-1 (ST129) or SWW33 (ST375)-colonized mice developed severe intestinal disease characterized by increased production of the pro-inflammatory cytokines granulocyte-macrophage colony-stimulating factor (GM-CSF), interleukin-6 (IL-6), and interferon-gamma (IFN-γ)." (PMID 30356663, 2018). "Hence, we hypothesized that Shaoyao decoction can protect against intestinal ulcers by modulation Th17/Treg imbalance through the IL-6/STAT3 signaling pathway." (PMID 38001450, 2023). "Since acute CWIR could occur in some special working populations (such as military, lifeguards, etc.)or extreme distress situations (such as floods, snowstorms, etc.)in reality, this work may provide more theoretical basis for the treatment of CWIR-related intestinal disorders via IL-6 signaling." (PMID 36505466, 2022). "Moreover, weaning is associated with upregulation of IL-1, Il-6, and TNF-α in the intestine, and this early inflammatory response may contribute to both anatomical and functional intestinal disorders in piglets." (PMID 25101851, 2014). "Pro-inflammatory cytokines, such as IL-1β, IL-6, and TNF-α, serve to stimulate inflammatory responses and promote the occurrence of intestinal diseases." (PMID 36359981, 2022).
intestinal diseases (continued). "Therefore, IL-6/STAT3 signaling pathway is important for intestinal homeostasis maintenance, and regulation of this signaling is an approach in treatment of intestinal disorders." (PMID 34337082, 2021).